LPL (lipoprotein lipase)
Diseases named in the same sentence as LPL in open-access papers (continued):
Sharing a sentence is not in itself a finding about the gene and the disease.
hypertriglyceridemia (continued). "A previous study has demonstrated that the siRNA-mediated knockdown of liver ANGPTL3 relieved its inhibitory effect on LPL and significantly reduced hypertriglyceridemia and oxidative stress in nephrotic rats." (PMID 39088466, 2024). "One case study reported acute pancreatitis secondary to severe hypertriglyceridemia due to a transient reduction in lipoprotein lipase (LPL) activity in a patient who recently recovered from COVID-19." (PMID 38979030, 2024). "Hypertriglyceridemia (HTG) is a complex disorder caused by genetic and environmental factors that frequently results from loss-of-function variants in the gene encoding lipoprotein lipase (LPL)." (PMID 38911039, 2024). "ApoC3 is an inhibitor for LPL-mediated lipolysis, and increases in apoC3 activity contribute to the development of hyperglyceridemia." (PMID 39234305, 2024). "IL-6 and IL-1 β are involved in IR, which is mediated through the underexpression of insulin receptor substrate-1 (IRS-1), and also suppress the activity of lipoprotein lipase, resulting in hypertriglyceridemia." (PMID 39063997, 2024). "Several studies have shown that increased LPL activity can ameliorate obesity; overexpression of LPL protects against diet-induced hypertriglyceridemia and hypercholesterolemia." (PMID 39590382, 2024). "Polymorphisms in the lipoprotein lipase (LPL) and apolipoprotein CII (APO CII) genes have been linked to severe hypertriglyceridemia in several populations." (PMID 37954769, 2023). "Finally, we considered the fact that ApoC2 is a critical activator of LPL activity as shown by the fact that ApoC2 deficiency results in severe hypertriglyceridemia and wondered what the effects of ANGPTL4/8-mediated plasmin generation might be on ApoC2-mediated stimulation of LPL activity." (PMID 37666362, 2023). "Decreasing plasma triglycerides (TGs) by activating lipoprotein lipase (LPL) with ApoC2 mimetic peptides is a new treatment strategy for hypertriglyceridemia." (PMID 37547254, 2023). "Lipoprotein lipase-null mice exhibit severe hypertriglyceridemia, reduced high-density lipoprotein levels, and neonatal death." (PMID 37233656, 2023). "Despite the lack of APO A5 and APO B frequencies, this study demonstrated an association between LPL-Hind III polymorphism and hypertriglyceridemia, which renders Kurdish patients more susceptible to hypertriglyceridemia." (PMID 37954769, 2023). "On the other hand, the positive correlation of TAC with triglycerides is consistent with in vivo studies where TAC is positively correlated with LPL activity (r = 0.979), an enzyme whose activity increases in the presence of hypertriglyceridemia." (PMID 37627507, 2023). "Of note, some chemotherapies, such as tamoxifen and asparaginase, inhibit LPL activity but also lead to hypertriglyceridemia." (PMID 36652113, 2023). "Lipoprotein lipase (LPL), a crucial enzyme in the intravascular hydrolysis of triglyceride-rich lipoproteins, is a potential drug target for the treatment of hypertriglyceridemia." (PMID 37043509, 2023). "Triglycerides and HDL-c levels stratified by LPL-Hind lll and APO Cll-Ava ll polymorphisms in patients with severe hypertriglyceridemia." (PMID 37954769, 2023). "The main factor in the development of hypertriglyceridemia is an impaired clearance, presumably because of LPL dysfunction." (PMID 37892400, 2023). "It has been proposed that CCDC80 increases hypertriglyceridemia by decreasing the expression of LPL, a key catalyst in hydrolysis of TGs." (PMID 37224770, 2023). "Peptides were first tested for their ability to activate LPL and then in hypertriglyceridemia mouse models." (PMID 37547254, 2023). "This study investigated the frequency of LPL-Hind lll and APO Cll-Ava ll polymorphism among Kurdish patients with severe hypertriglyceridemia." (PMID 37954769, 2023). "Our studies revealed that the severe hypertriglyceridemia in Apoa5–/– mice was accompanied by substantial reductions in LPL mass and activity in the postheparin plasma." (PMID 37824203, 2023).
hypertriglyceridemia (continued). "The LCT-restricted/MCT-supplemented diet, employed for over a decade at our institution, appears to be amenable for the management of hypertriglyceridemia > 20 mmol/L in LPL patients." (PMID 37630727, 2023). "In diabetes, the impairment of insulin secretion and insulin resistance contribute to hypertriglyceridemia, as the enzymatic activity of lipoprotein lipase (LPL) depends on insulin action." (PMID 37448184, 2023). "In both type 1 and 2 diabetes patients, reduced or deficient insulin secretion and insulin resistance contribute to hypertriglyceridemia, as the enzymatic activity of lipoprotein lipase (LPL) depends on insulin action." (PMID 37448184, 2023). "GPIHBP1 autoantibodies block the LPL binding to GPIHBP1‐transfected Chinese hamster ovary cells, suggesting that GPIHBP1 autoantibodies functionally blocked LPL‐mediated processing of TRL, causing severe hypertriglyceridemia." (PMID 37448184, 2023). "Chylomicrons, VLDL-C, and LDL-C build up in the plasma due to impaired LPL activity or expression, resulting in hypertriglyceridemia." (PMID 37425327, 2023). "A deficiency in LPL or GPIHBP1 impairs triglyceride hydrolysis and induces severe hypertriglyceridemia." (PMID 36837768, 2023). "Because APOC3 is an LPL inhibitor, the insulin-independent upregulation of APOC3 inhibits LPL, which reduces the hydrolysis of chylomicron, leading to hypertriglyceridemia." (PMID 37304843, 2023). "This apolipoprotein reflects insulin sensitivity and negatively modulates LPL activity driving plasma levels of triglycerides and being a target of drugs for hypertriglyceridemia control." (PMID 36899434, 2023). "When the activity of LPL is affected, it would consequently result in hypertriglyceridemia, which is a pivotal trait of nephrotic syndrome." (PMID 36387855, 2022). "Previous studies have shown that infection and inflammation induce hypertriglyceridemia due to inhibition of serum clearance by lipoprotein lipase, a key enzyme in triglyceride catabolism." (PMID 35628907, 2022). "IL-6, IL-1, and TNF-α are responsible for fever, whereas interferon-γ and TNF-α contribute to hypertriglyceridemia by inhibiting lipoprotein lipase and stimulating triglyceride synthesis." (PMID 35244052, 2022). "The increasing levels of inflammatory factors suppressed lipoprotein lipase (LPL) activity, contributing to hypertriglyceridemia." (PMID 35860700, 2022). "We anticipate that the hypertriglyceridemia and hypercholesterolemia noticed in Cd-treated animals were attributed to the reduced activity of plasma lipoprotein lipase, a pivotal enzyme, in their breakdown." (PMID 36003506, 2022). "Most variants interfering with triglyceride metabolism and causing hypertriglyceridemia are loss of function variants (LOF), and mainly found in the LPL, APOC2, APOA5, LMF1 and GPIHBP1 genes." (PMID 35237305, 2022). "Severe hypertriglyceridemia, in the form of Familial Chylomicronaemia Syndrome (FCS), is a rare autosomal recessive disease caused by pathogenic variants especially in the LPL gene but also in APOC2, APOA5, LMF1 and GPIHBP1." (PMID 35237305, 2022). "Both the clinical and in vitro data suggest that severe hypertriglyceridemia was of digenic origin caused by LMF1 and LPL mutation double heterozygosity in this patient." (PMID 35368694, 2022). "Apo CII is a lipoprotein lipase (LPL) cofactor, the enzyme that hydrolyzes triglycerides, and apo-CII deficiency stimulates hypertriglyceridemia, an independent atherosclerosis risk factor." (PMID 35205153, 2022). "Hypertriglyceridemia is a hallmark lipid abnormality in patients with CKD and mainly results from the dysfunction of lipoprotein lipase (LPL) and hepatic lipase that are responsible for the degradation of TG-rich chylomicron and low-density lipoprotein (VLDL)." (PMID 36440016, 2022). "Hypertriglyceridemia in HLH is thought to be secondary to decreased lipoprotein lipase activity, which was initiated by increased TNF-α levels." (PMID 35410268, 2022).
hypertriglyceridemia (continued). "In patients with hypertriglyceridemia, low plasma LPL activity and quality have been found, and this phenomenon is usually caused by pathogenic LPL variants." (PMID 35923617, 2022). "Unexpectedly, however, most of the GPIHBP1 and LPL in the mutant mice was located on the abluminal surface of ECs (explaining the hypertriglyceridemia)." (PMID 35229724, 2022). "FCS is a rare disease (1:1,000,000 for homozygote and 1 in 500 for heterozygote) inherited in an autosomal recessive manner (genetic causes of hypertriglyceridemia are grouped under FCS) and is mainly due to lipoprotein lipase (LPL) gene mutations." (PMID 35207255, 2022). "The combined effect of these factors sets the actual LPL activity, which determines the extent of triglyceride degradation and thus has a significant impact on the development of hypertriglyceridemia." (PMID 35144640, 2022). "A GWA study of individuals with hypertriglyceridemia has shown that common variants in 4 genetic loci (APOB, LPL, GCKR, and APOA5) are significantly related to increased TG levels." (PMID 35999587, 2022). "In this study, two patients with severe hypertriglyceridemia were confirmed to have type I hyperlipoproteinemia by whole-exome sequencing (WES), and two novel compound heterozygous variants of the LPL gene were identified." (PMID 35923617, 2022). "In diabetes, lipoprotein lipase activity is inhibited due to insulin insufficiency, which promotes hypertriglyceridemia." (PMID 35345832, 2022). "Lipoprotein lipase releases free fatty acids carried in circulating chylomicrons and VLDLs to the muscle cells and adipose tissue, and its inhibition leads to hypertriglyceridemia that provokes atherosclerotic plaque formation." (PMID 34684048, 2021). "Increased levels of apoCIII induce hypertriglyceridemia by inhibiting LPL activity and hepatic clearance of circulating lipids by blocking liver lipoprotein receptors." (PMID 35008488, 2021). "This study aimed to explore the association between a novel lipoprotein lipase (LPL) mutation and severe hypertriglyceridemia in a GSD Ib infant with severe hypertriglyceridemia." (PMID 34485189, 2021). "In cachexic subjects, sustaining catabolism and inflammation will accelerate the production of TNF-ɑ, IL-6 and IL-1 to block lipoprotein lipase and the L-carnitine-induced fatty acid transfer system, leading to hypertriglyceridemia and hypercholesterolemia." (PMID 34724970, 2021). "The main known function of ApoC-III is to inhibit the activity of lipoprotein lipase, delaying the clearance of triglyceride-rich lipoproteins (VLDL and chylomicrons) and has been associated with increased risk of hypertriglyceridemia and poor CVD outcomes." (PMID 34373542, 2021). "These events, including inhibition of lipoprotein lipase by arsenic results in hypertriglyceridemia and hypercholesterolemia." (PMID 33827703, 2021). "The aim of the study was to assess the impact of HDL-2 and HDL-3 on lipoprotein lipase (LPL)-mediated very-low-density lipoprotein (VLDL) catabolism related to hypertriglyceridemia development." (PMID 34944655, 2021). "The first mechanism by which TNF-α increases TG’s plasma concentration is the inhibition of LPL activity, leading to a decrease clearance of TG-rich lipoproteins like very-low-density lipoprotein (VLDL), and thereby causing hypertriglyceridemia." (PMID 34300308, 2021). "Deficiency in either LPL or GPIHBP1 impairs TG hydrolysis, resulting in severe hypertriglyceridemia." (PMID 34036306, 2021). "Beyond this threshold, ingestion or infusion of triglycerides can increase hypertriglyceridemia and “clog” lipoprotein lipase (enzyme responsible for the breakdown of triglyceride-rich lipoproteins) by saturating its activity." (PMID 34371943, 2021). "Both ANGPTL3 and ANGPTL8 interact as regulators of LPL activity, and both are targets for pharmacotherapeutic agents currently undergoing testing as potentially effective drugs in the treatment of hypertriglyceridemia." (PMID 34959891, 2021).
hypertriglyceridemia (continued). "In hypertriglyceridemia caused by elevated ApoC-III levels, the VLDL concentration in plasma increases due to a dual impact of ApoC-III: (i) decreased LPL activity and (ii) enhanced synthesis and hepatic secretion of VLDL." (PMID 34356847, 2021). "With the discovery of GPIHBP1, the pathway for LPL transport and distribution in the intravascular unit changed radically and new etiologies for both inborn and acquired hypertriglyceridemia were outlined." (PMID 34336854, 2021). "APOCIII is now recognized as a key regulator in severe hypertriglyceridemia due to its inhibition of lipoprotein lipase (LPL) and hepatic lipase." (PMID 34721061, 2021). "CKD patients have a lower activity of lipoprotein lipase and hepatic TG lipase, which likely leads to the development of hypertriglyceridemia, and subsequently to augment renal impairment." (PMID 32774441, 2020). "ANGPTL4 can delay the clearance of TG in the circulation by inhibiting LPL, leading to hypertriglyceridemia." (PMID 32280690, 2020). "We found 0.2% of individuals with severe hypertriglyceridemia had large-scale CNVs involving large portions of the LPL gene." (PMID 32793115, 2020). "In 2010, we showed a 2-fold enrichment of rare heterozygous variants in four candidate genes, including LPL and APOA5 in patients with hypertriglyceridemia." (PMID 32793115, 2020). "ANGPTL4 is known to inactivate LPL, which reduces triglycerides (TG) conversion to free fatty acids, leading to hypertriglyceridemia." (PMID 32638512, 2020). "Lipoprotein lipase (LPL) hydrolyzes triglycerides in lipoprotein to supply fatty acids, and its deficiency leads to hypertriglyceridemia, thereby inducing metabolic syndrome (MetSyn)." (PMID 31234537, 2019). "It was found that TNF-α can suppress lipoprotein lipase synthesis, contributing to hypertriglyceridemia due to decrease of peripheral clearance rate of triglyceride." (PMID 31178854, 2019). "With regard to LPL, LPL-deficient human subjects had low levels of HDL cholesterol and hypertriglyceridemia, accompanied by increased levels of acylation-stimulating protein." (PMID 31234537, 2019). "In insulin resistant status, failure to inhibit MPL and activate LPL would lead to hypertriglyceridemia." (PMID 31794594, 2019). "The proposed mechanism in this regard is that insulin deficiency under diabetic conditions increases the levels of chylomicron and LDL-C, but decreases the activity of lipoprotein lipase, which finally results in hypertriglyceridemia." (PMID 31168341, 2019). "Hypertriglyceridaemia in CKD is thought to be due to the dysregulation of various enzymes such as lipoprotein lipase (LPL) and hepatic lipase, apolipoproteins such as apoC III and apoC II and receptor such as VLDL-receptor involved in triglycerides metabolism." (PMID 31752737, 2019). "CREBH also regulates FGF21, which stimulates LPL-mediated TG clearance, thereby contributing to hypertriglyceridemia in CREBH KO mice." (PMID 29738435, 2018). "ApoCIII has been confirmed to decrease lipoprotein lipase (LPL) activity and result in hypertriglyceridemia, which is an independent risk factor for atherosclerosis." (PMID 30053815, 2018). "In circulation, apoCIII, mainly residing on the surface of HDL and TRLs, inhibited LPL activity and disrupted TRLs clearance, thereby leading to hypertriglyceridemia." (PMID 30021607, 2018). "Some recent reports suggested a combination of intravenous heparin and insulin infusion in severe cases of gestational hypertriglyceridemia-induced AP, which increased the lipoprotein lipase activity." (PMID 29443736, 2018). "For example, TCDD reduces expression of lipoprotein lipase promoting hypertriglyceridemia, inhibiting glucose transport/LPL activity and increasing secretion of TNF." (PMID 29064461, 2017). "This event involves the elevated transfer of TAG to HDL owing to hypertriglyceridemia caused by increased VLDL hepatic synthesis and decreased lipoprotein lipase (LPL) activity." (PMID 28913361, 2017).
hypertriglyceridemia (continued). "Treatment of severe hypertriglyceridemia with heparin is controversial due to a transient rise in LPL followed by increased degradation and depletion of plasma stores resulting in LPL deficiency." (PMID 28225998, 2017). "Even the subtlest increase of plasma APOE concentration from physiological (2–5 mg/dL), triggers severe hypertriglyceridemia that is due to direct inhibition of plasma LPL activity and increased hepatic VLDL production." (PMID 29770778, 2017). "Previous works support our data and demonstrated the link between iron status and lipid metabolism, in particular the ability of free iron to inhibit lipoprotein lipase activity and consequently hypertriglyceridemia." (PMID 28903761, 2017). "By contrast, apoC-III interferes with apoC-II–mediated activation of LPL, and thereby promotes hypertriglyceridemia." (PMID 28209220, 2017). "The genetic testing revealed compound heterozygote mutations in the lipoprotein lipase (LPL) gene for patient A and two known compound heterozygote LPL gene mutations for the patient B. FCS is the most dramatic example of severe hypertriglyceridemia." (PMID 27153815, 2016). "The direct implication of the ANGPTL3-4-8 model is that when ANGPTL8 is increased, LPL activity will be suppressed in the heart and skeletal muscle, resulting in accumulation of TG in the circulation (hypertriglyceridaemia)." (PMID 27053679, 2016). "In Gpihbp1 knockout (KO) mice, LPL is mislocalized to the interstitial spaces surrounding myocytes and adipocytes, and the KO mice exhibit severe hypertriglyceridaemia (chylomicronaemia)." (PMID 27053679, 2016). "ANGPTL4-related LPL activity inhibition caused the inhibition of LPL-dependent VLDL lipolysis, leading to hypertriglyceridemia." (PMID 26690452, 2015). "Too much apoE stimulates very low-density lipoproteins production in the liver and impairs lipoprotein lipase-mediated lipolysis, leading to hypertriglyceridemia." (PMID 25852220, 2015). "The zeolite nanoparticles can potentially be used for selectively capture of APOC-III in order to reduce the activation of lipoprotein lipase inhibition during hypertriglyceridemia treatment." (PMID 26616161, 2015). "In the present study, either DSS administration or adenoviral LPL expression which similarly increased plasma TG-hydrolysis activity in obese KK-Ay mice, markedly improved hypertriglyceridemia." (PMID 26268630, 2015). "In patients with diabetes, lowering levels of active lipoprotein lipase (which is an insulin-dependent enzyme) promotes postprandial hypertriglyceridemia and leads to increased levels of small, dense LDLs that are oxidized readily." (PMID 25995772, 2015). "Hepatic DN-S6K expression markedly ameliorated hypertriglyceridemia in KK-Ay mice with increased adipose LPL expression and increased serum TG clearance after Intralipid injection." (PMID 26268630, 2015). "In summary, the present study demonstrates that reducing hepatic ApoA5 expression in mice by ASO treatment reduces LPL activity leading to hypertriglyceridemia and decreased lipid uptake by liver, muscle, and WAT." (PMID 25548259, 2015). "The two types zeolites can potentially be used for selectively capture of APOC-III, and to reduce the activation of lipoprotein lipase inhibition in hypertriglyceridemia treatment." (PMID 26616161, 2015). "These FFAs lead to hypertriglyceridemia by inhibiting lipoprotein lipase in adipose and muscle tissues, in addition to increased production of very-low-density lipoprotein (VLDL) and TG in the liver." (PMID 26831558, 2015). "The neonatal death, together with the hypertriglyceridemia, are prevented by overexpression of human LPL in either skeletal or cardiac muscle." (PMID 26044956, 2015). "KK-Ay mice also exhibited remarkable hypertriglyceridemia in the fed state with decreased LPL expression in WAT." (PMID 26268630, 2015).